CCN2 (cellular communication network factor 2)
Diseases named in the same sentence as CCN2 in open-access papers (continued):
Sharing a sentence is not in itself a finding about the gene and the disease.
tumor (continued). "In accordance with these studies, we discovered that CCN2 expression is related to more infiltrative growth without tumor capsule and worse DFS in HCCs." (PMID 25126747, 2014). "In conclusion, the expressions of CCN2, EMA, and FAP may be involved in the formation of tumor fibrous stroma, along with activation of CAFs in HCC, giving rise to aggressive behavior." (PMID 25126747, 2014). "Although CCN2 is well known as fibrogenic cytokine, to our knowledge, no study has reported on a relationship between CCN2 expression and tumor fibrous stromal components in HCC." (PMID 25126747, 2014). "Based on these transcriptomic results, suppression of CCN2, FGFR2, and SELE may inhibit tumor proliferation, metastasis, or angiogenesis, while upregulation of CDH1 and CXCL10 could enhance cellular adhesion and antitumor immune responses, offering promising avenues for therapeutic intervention." (PMID 40724877, 2025). "Notably, we found that the FAP+ fibroblasts secreted CCN2, previously reported as a coactivator of the TGF-β pathway via direct binding to TGF-β, cooperating with TGF-β to activate the pathway, thus promoting the transition of tumor cells into the EMT-subtype." (PMID 39095854, 2024). "Last, given the involvement of CCN2 in bone metastasis regardless of the of primary tumour site, its level in biological fluid could provide a precocious marker of skeleton related events." (PMID 34228239, 2021). "However, there remains a lack of knowledge of CCN2/CTGF role/functions in cancer progression in vivo in the MMP3 switching on CCN2/CTGF gene as well as the role of the C-terminus of CCN2/CTGF cleaved by MMP3 and their spatial distribution during activation and tumor progression." (PMID 32260433, 2020). "In addition, CTGF/CCN2 was proven to have an oncogenic role in HCC; it contributes to tumor-stromal crosstalk, and promotes tumor cell growth, dedifferentiation, resistance to doxorubicin, and expression of inflammation-related proteins that contribute to carcinogenesis." (PMID 27011166, 2016). "In tumor epithelial cells from cohort 1, CCN2 and EMA were expressed in 15.3% and 17.2%, respectively, and their expressions were more frequent in HCCs with fibrous stroma (≥5% of tumor area) than those without (P<0.05 for all); CCN2 expression was well correlated with K19 and EMA expression." (PMID 25126747, 2014). "Furthermore, MSCC WT keratinocytes showed an increased expression of CCN2 when the conditions that occur during DMBA/TPA treatment were mimicked by application of either TPA or IL-6, the cytokine up-regulated during DMBA/TPA tumorigenesis and crucial for tumor formation." (PMID 32423907, 2020). "The expression of CCN2 was correlated with absence of capsule formation, which is a characteristic pathological feature of invasive tumor growth, as well as frequent K19 expression (cohort 1), larger tumor size (cohort 2), and shorter disease free survival (cohort 1 and 2)." (PMID 25126747, 2014). "Moreover, we identified Smad7 as a putative negative regulator of both CCN2 and type I collagen gene expression in fibroblasts, with Smad7 mRNA and protein levels being significantly increased in CCD-1068SK fibroblasts that were directly co-cultured with MDA-MB-231 tumour cells." (PMID 24090133, 2013). "The results obtained in these studies suggest that the decreased CCN2 and type I collagen matrix production and increased MMP expression observed in our model system of co-cultured CCD-1068SK fibroblasts could facilitate MDA-MB-231 tumour cell invasion through the ECM." (PMID 24090133, 2013). "A study using a different CCN2 inhibitory agent, FG-3019, found that the antibody was able to promote KPC tumor response to gemcitabine, without improving drug distribution." (PMID 32294968, 2020).
tumor (continued). "Although CCN2 could be detected in all K19 Itga3 WT tumors analyzed, a small number of CCN2-positive cells (the mean CCN2-positive surface is 0.27% of total tumor area) together with their non-HB origin indicates that CCN2 does not play a major role in the late stages of tumor growth." (PMID 32423907, 2020). "Analysis of gene expression by quantitative real-time RT-PCR in indirectly co-cultured CCD-1068SK fibroblasts revealed that tumour cells did not influence the expression of COL1A1, COL1A2, CCN2 or Smad7 when compared to fibroblast monocultures." (PMID 24090133, 2013). "CCN2/CTGF has been identified as an independent prognostic indicator of both tumor recurrence and overall survival for intrahepatic CCA patients regardless of tumor location, tumor grade, or vascular and perineural invasion." (PMID 27829832, 2016). "CCN2, EMA, and K19 expression was noted in tumor epithelial cells, but not in CAFs." (PMID 25126747, 2014). "It is also not surprising that higher expression of CCN2 and the connective tissue growth factor (CTGF) was noted in HNSCC tissues than in normal adjacent non-cancerous tissues, and this may contribute to the higher aggressiveness of TSCC cells via the promotion of tumour development." (PMID 39120301, 2024).
cancer (333 papers, 2004 to 2026). A tumor composed of atypical neoplastic, often pleomorphic cells that invade other tissues. "CCN2, also known as connective tissue growth factor, regulates proliferation, differentiation, and migration in normal physiology and has been implicated in cancer cell proliferation, adhesion, drug resistance, and metastasis." (PMID 41303528, 2025). "In pathological conditions, dysregulated CCN2 has been associated with cancer, cardiovascular disease, and tissue fibrosis." (PMID 33662577, 2021). "CCN2 and its fragments also have been implicated in the regulation of a multitude of biological phenomena in cancers, which was not only associated with fibrosis, but also with mesenchymal stem cells." (PMID 33833779, 2021). "CCN2 has been implicated in more than 25 different forms of cancer, mostly based on correlations (either positively or negatively) with clinical outcome." (PMID 33428075, 2021). "CCN2 plays a role in many diseases, especially those associated with fibrosis, but has also been implicated in many different forms of cancer." (PMID 33428075, 2021). "Both MMP7 and CCN2 have been associated with poor prognosis in different types of cancer and with fibrotic or inflammatory diseases." (PMID 29941541, 2018). "CCN2 mRNA levels and their association with prognosis also vary across different types of cancer." (PMID 33833779, 2021). "The overexpression of Cyr61 (CCN1) in the low-metastatic variant of the human SaOS-2 OS cell line increased cell proliferation and promoted lung metastasis, and both Cyr61 and CTGF (CCN2) have been implicated in the progression of bone metastases in other cancers." (PMID 31878963, 2019). "CCN2 expression has been linked to drug resistance in several types of cancer." (PMID 27613407, 2016). "In many types of cancer, CCN2 overexpression has been associated with poor outcome." (PMID 27613407, 2016). "Other proteins are known inducers of epithelial to mesenchymal transition (EMT) (i.e. Laminins) or cancer cell spreading (i.e., CCN2, NPNT, WASF2, SERPINE, MAP4K4)." (PMID 40410902, 2025). "A growing body of evidence underscores the roleof CCN2 in promoting cancer initiation, progression, and metastasisthrough its regulation of cell proliferation, migration, invasion,drug resistance, epithelial–mesenchymal transition (EMT), andangiogenesis." (PMID 38809962, 2024). "As a member of the CCN family, CTGF (also known as CCN2) is an essential regulator in the progression of various diseases, including fibrosis, cancer, neurological disorders, and eye diseases." (PMID 38731911, 2024). "Previous studies have shown that CCN1 and CCN2 play functional roles in the development of different types of cancers." (PMID 38545253, 2024). "Among the non-NFκB/TNF hallmark genes that received votes across all 16 cancer types, four genes (SRGN, CCN2, TNFRSF12A, and ZFP36L1) with an average vote exceeding 900 have been reported as regulated by TNF and NFκB." (PMID 37475016, 2023). "Of the EMT pathway, the genes IL-6, SFRP4, FZD8, ADAM12, and CCN2 are known to promote cancer cell invasion and migration in multiple types of cancers." (PMID 35505422, 2022). "Different studies have shown that integrins are involved in CCN2 downstream signaling responses, which turns out to be relevant in some disorders such as cancer." (PMID 35204752, 2022). "Tafazzin is a co-activator of the Hippo pathways, which is responsible for the transcription of multiple tumorigenesis genes (such as cyclin D1 and CCN2 (connective tissue growth factor)); thus, they are involved in cancer development and progression." (PMID 35008887, 2021). "CCN2 is a secreted growth factor that interacts with various ECM molecules and is known to promote HCC progression through increased proliferation of cancer-associated fibroblasts and increased migration of macrophages." (PMID 33995488, 2021).
cancer (continued). "CCN1 and CCN2 are aberrantly expressed in many types of cancer tissues and are involved in the processes of angiogenesis and tumorigenesis." (PMID 28460443, 2017). "CCN2 can positively modulate expression of matrix metalloproteinases, which are critically involved in cancer metastasis." (PMID 29029514, 2017). "Collectively, investigation of CCN2 will enrich the database of ECM-targeted strategies for cancer treatment." (PMID 29029514, 2017). "CCN2, is well-known for its involvement in connective tissue remodeling in various diseases, including cancer." (PMID 27613407, 2016). "CCN2 also has a role in cancer cell biology and has been shown to promote cell proliferation, colony formation, migration and angiogenesis in a cell type-specific manner." (PMID 25541962, 2014). "CCN2 (also known as CTGF), is a secreted protein that binds to integrins, modulates the invasive behavior of certain human cancer cells." (PMID 24637722, 2014). "Overexpression of CCN2 protected cisplatin- or doxorubicin-mediated cell death in these cancer cells." (PMID 24637722, 2014). "In various cancers, hypoxia and CCN2 promote stem and progenitor cell properties, and regulate the proliferation, migration and phenotype of cancer cells." (PMID 25541962, 2014). "DNA methylation of the CCN2/CTGF genomic sequence has already been reported in several cancers, but a detailed target sequence for DNA methylation contributing for gene silencing had never been described." (PMID 25120383, 2014). "Notably, CCN2 is considered a promising therapeutic target, and several CCN2 inhibitors, such as pamrevlumab (FG-3019), have already entered clinical trials for fibrotic disease and cancer." (PMID 40724877, 2025). "Therefore, both YAP and CCN2 are considered therapeutic targets in cancer and their inhibitors are being evaluated preclinically as well as clinically in different cancer and disease conditions." (PMID 40157909, 2025). "Considering the multifaceted role of CCN2 in cancer, modulating its activity could be explored for therapeutic purposes." (PMID 40788820, 2025). "A 2.7-fold increase in CCN2 expression was documented by microarray analysis of hepatocytes isolated from 35-week Pten knock-out mice, which develop NASH-like liver pathology leading the authors to speculate that CCN2 was involved in NASH fibrosis or cancer." (PMID 37629004, 2023). "CCN2 is also involved in angiogenesis, cancer, inflammation, and fibrogenesis." (PMID 35204752, 2022). "Thus, these bioinformatics results further revealed the heterogeneous expression and function of CCN2 in different types of cancer." (PMID 33833779, 2021). "CYR61/CCN1 and CTGF/CCN2 are variably deregulated in human cancers." (PMID 33670622, 2021). "CCN2 overexpression is related to poor prognosis in most types of cancer." (PMID 33833779, 2021). "PDAC cancer cells with upregulated CTGF/CCN2 evade hypoxia-mediated apoptosis." (PMID 33050151, 2020). "To examine whether MMP3 and/or CCN2/CTGF expression are correlated with the prognosis of patients suffering from these types of cancers, we carried out survival analyses using the Kaplan–Meier plot." (PMID 32260433, 2020). "In addition, CKAP4 translocated to the nucleus of T24 cells and regulated the CCN2 expression after APF treatment (CCN2 overexpression inhibits invasion and metastasis of the cancer cells both in vitro and in vivo)." (PMID 33614703, 2020). "Furthermore, the increase in CCN1/CCN2 expression contributes to the S1P-induced increase in cancer cell proliferation." (PMID 28460443, 2017). "In addition to benign fibrotic processes, CCN2 overexpression is also known to be responsible for pathologic fibrosis, including desmoplastic reaction in cancer." (PMID 25126747, 2014). "For this reason, the occurrence of metastasis in cancer is an important issue nowadays, and CCN2/CTGF could be an important target for its attenuation or prevention." (PMID 25120383, 2014).
cancer (continued). "In addition, here we intend to discuss recent discoveries and a new strategy to develop therapies against CCN2/CTGF, in order to treat cancer metastasis." (PMID 25120383, 2014). "We first assessed expression of CCN family members, CCN1, CCN2, CCN3 and CCN5 which have been implicated in modulating cell proliferation, cell adhesion, angiogenesis, cell migration, metastasis and epithelial-mesenchymal transition in a variety of cancers." (PMID 25541962, 2014). "CCN2 is expressed by mesenchymal cells undergoing active tissue remodelling, and is characteristically overexpressed in connective tissue pathologies such as fibrosis and cancer." (PMID 21453480, 2011). "In addition, bioinformatics analyses of transcriptomic datasets from Cancer Cell Line Encyclopedia database revealed significantly positive associations between USP7 expression and CYR61/CCN1 (R = 0.4498, p < 0.0111), CTGF/CCN2 (R = 0.3141, p < 0.0426) in 31 HNSCC cell lines." (PMID 35931679, 2022). "Therefore, CCN2 protect chemoresistance is a general phenomenon in human cancer cells." (PMID 24637722, 2014). "The STRN4 palmitoylation reduced YAP phosphorylation, promoted nuclear translocation of YAP and activated downstream Hippo pathway transcriptional targets—including CCN1, CCN2 and ANKRD1—thereby driving cancer cell migration." (PMID 40903842, 2025). "In vitro, MMP-3-enriched extracellular vesicles from a metastatic murine cancer cell line LuM1 activated the promoter and production of the matricellular protein CTGF (connective tissue growth factor, aka CCN2) in “recipient” cells." (PMID 35163805, 2022). "CCN2/CTGF is the most studied of the CCN family proteins by virtue of its widespread expression pattern and importance in fibrovascular diseases and cancer." (PMID 32429045, 2020). "EVs derived from a rapidly metastatic cancer cell line (LuM1) were enriched in MMP3 and a C-terminal half fragment of CCN2/CTGF." (PMID 32260433, 2020). "A high expression level of MMP3 or CCN2/CTGF mRNA was prognostic and unfavorable in particular types of cancers including head and neck, lung, pancreatic, cervical, stomach, and urothelial cancers." (PMID 32260433, 2020). "In fact, both CCN2 and fibronectin belong to ECM ligands of integrin, an important receptor contributing to cancer development and drug resistance." (PMID 29029514, 2017). "Because CK19 positive HCC has been described as a cancer originating from HPC, these results support a role for CCN2/CTGF in HPC activation during IH-CCA and HCC tumorigenesis." (PMID 27829832, 2016). "Altered expressions of CCN1/CYR61, CCN2/CTGF, CCN3/NOV, and CCN4/WISP1 were found to correlate with clinical features, including venous invasion, cellular differentiation, TNM staging for malignant tumors, disease-free survival, and overall survival in HCC." (PMID 27829832, 2016). "Connective tissue growth factor (CTGF/CCN2), a secreted protein, binds to integrins, modulates invasive behavior of certain human cancer cells." (PMID 25003330, 2014). "Since its identification, CCN2/CTGF’s role has been studied, in a large variety of biological phenomena, especially in cell chemotaxis, migration, adhesion and cancer." (PMID 25120383, 2014). "Targeting YAP and/or CCN1 and CCN2 may provide clinical benefit in BCC and other cancers in which YAP is elevated." (PMID 39898007, 2025). "Consistent with the observed IAG933 activity in a subset of Hippo-unaltered cell lines, additional profiling on 263 cancer cell lines revealed higher sensitivity in cells that display high basal TEAD activity, as determined by a four-gene (CCN1, CCN2, ANKRD1 and AMOTL2) transcriptional signature." (PMID 38565920, 2024). "Indeed, we highlighted three pan-cancer NFκB/TNF hallmark genes (EGR1, JUNB, and ZNF36) and identified four candidates (SRGN, CCN2, TNFRSF12A, and ZFP36L1) that are highly potentially involved in NFκB/TNF pathways in various cancers." (PMID 37475016, 2023).
cancer (continued). "Based on the findings in other cancer types, and on the notion that CMS4 tumors are stroma-rich and have a poor prognosis, we suggest that CCN2 could also play a role in the fibrotic response that characterizes CMS4 CRC." (PMID 27613407, 2016). "In cancer and in metastasis, the role of CCN2/CTGF seems to be the same." (PMID 25120383, 2014). "Although the role of CCN2 in normal tissue fibrosis has been well-studied, the function of CCN2 in cancer is not as well-understood." (PMID 21955589, 2011). "In the field of cancer research, especially for HCC, the negative role of CCN2 and the interaction regulation mechanism between CCN2 and LRP6 are still unclear." (PMID 28870205, 2017). "CCN2 is a protein belonging to the cellular communication network (CCN) family; high levels of CCN2 have been observed in normal tissue repair and pathologies, including cancers, while it is not expressed by dermal fibroblasts." (PMID 39199632, 2024). "Unlike its original name (“CTGF”) suggested, CCN2 is not an actual growth factor but a matricellular protein that plays an important role in fibrosis, inflammation and connective tissue remodeling in a variety of diseases, including cancer." (PMID 27613407, 2016).
kidney disease (55 papers, 2006 to 2025). "Although the CCN2 deficiency has been observed to be beneficial in renal disease, it may be deleterious in other tissues and conditions." (PMID 40362638, 2025). "Our results identify CCN2 as a novel therapeutic target to modulate this pathway that should be explored further to design novel, more effective therapeutic approaches to kidney disease that reduce inflammation." (PMID 37627536, 2023). "Many studies using different strategies for blocking CCN2 activity have proven beneficial effects in experimental pathologies, including renal diseases." (PMID 35204752, 2022). "Our studies showing binding of the CCN2(IV) in tubular epithelial cells remark the importance of future studies evaluating the presence of CCN2 degradation products in kidney diseases." (PMID 35204752, 2022). "However, key differences between them have been described, with CCN2 being especially relevant in renal diseases." (PMID 35204752, 2022). "In the context of DN, a better understanding of the interplay between CCN2, a known effector of cytoskeletal reorganisation and TGFβ will undoubtedly enhance our understanding of the dysregulation of actin cytoskeletal processes in this kidney disease." (PMID 23902294, 2013). "Moreover, CCN2 may be a therapeutic target in experimental kidney diseases, as well as a potential biomarker for human CKD." (PMID 37627536, 2023). "Additionally, CCN2 has also been proposed as a potential therapeutic target for renal diseases." (PMID 35204752, 2022).